CDRT7 (CMT1A duplicated region transcript 7)
Synonyms: NCRNA00025; LINC00025
Gene: Long non-coding RNA gene on chromosome 17 (15,030,975 to 15,031,957, forward strand). Ensembl gene ENSG00000259944.
Diseases named in the same sentence as CDRT7 in open-access papers:
CDRT7 is named in the same sentence as 1 disease in open-access papers, as found by Europe PMC text mining. Sharing a sentence is not in itself a finding about the gene and the disease.
cancer (1 paper, 2023). A tumor composed of atypical neoplastic, often pleomorphic cells that invade other tissues.